LEP (leptin)
Diseases named in the same sentence as LEP in open-access papers (continued):
Sharing a sentence is not in itself a finding about the gene and the disease.
Insulin resistance (continued). "So, we concluded that vitamin D supplementation cannot alter insulin resistance directly, but it may have some beneficial consequences on diabetic patients due to its positive cardiovascular effects and leptin lowering properties." (PMID 33680012, 2020). "Irisin and leptin levels elevation can predict the insulin resistance in obese patients." (PMID 32544194, 2020). "Moreover, people with satisfactory cardiorespiratory fitness have been reported to possess high adiponectin and leptin concentrations, low amounts of abdominal subcutaneous fat and visceral fat, and reduced inflammation and insulin resistance." (PMID 32155732, 2020). "Similarly, sardine protein has been reported to lower plasma leptin and glucose levels and to improve the impaired glucose tolerance in rats with fructose-induced insulin resistance and metabolic syndrome." (PMID 33322303, 2020). "Thus, the effects of placental leptin on the mother may contribute to endocrine-mediated alterations in energy balance, such as the mobilization of maternal fat, which could further aggravate the insulin resistance associated with pregnancy and the onset of GDM." (PMID 32630697, 2020). "Furthermore, the knockdown of Ikbke gene improved leptin sensitivity, decreased food intake and increased energy expenditure, ameliorating insulin resistance." (PMID 32576879, 2020). "BAFF up-regulation, concomitant with activated BAFF signaling pathway, exhibited in SAT and BAT of leptin-deficient mice confirms that BAFF acts suppressively to non-shivering thermogenesis and may consequently result in exacerbation of insulin resistance." (PMID 32698539, 2020). "In mouse models of type 2 diabetes, leptin improved insulin resistance and hyperglycemia." (PMID 32131811, 2020). "Interestingly, serum leptin levels are positively correlated with insulin resistance (IR) raising the possibility that leptin is also involved in regulating IR." (PMID 31947687, 2020). "The NWO group had the higher mean serum levels of insulin (9.02 ± 4.75 vs. 6.24 ± 2.51, P = 0.009), leptin (17.31 ± 8.10 vs. 9.94 ± 4.30, P < 0.001) and homeostatic model assessment of insulin resistance (HOMA-IR) (33.77 ± 20.71 vs. 23.48 ± 10.03, P = 0.009) compared to the NWNO group." (PMID 33198735, 2020). "The results of this study may be a significant expectation among the forthcoming treatment strategies for leptin and insulin resistance." (PMID 31929574, 2020). "Analysis of the interactions of differentially expressed microRNAs with gene expression pathways suggests the potential contribution of selected miRNAs to the regulation of the activity of genes associated with insulin resistance, fatty acids metabolism, and adipocytokine (TNF-α, leptin) signaling." (PMID 32069846, 2020). "Since leptin may induce insulin resistance, the significant decrement on leptin levels in HF+A mice may also contribute to amelioration of insulin resistance that we observed in these animals." (PMID 33287102, 2020). "Therefore it is thought that improving impacts of the AGE-restricted diet on insulin resistance be related to its reduction impacts on inflammatory processes, oxidative stress and leptin levels along with an increased in adiponectin and sirtuin-143,44." (PMID 33335235, 2020). "In patients with compensated HCV-associated cirrhosis, insulin resistance but not the serum levels of adiponectin and leptin predicted the occurrence of HCC and of liver-related death or transplantation." (PMID 33167521, 2020). "Besides, leptin and insulin resistance increase ovarian sensitivity to LH and contribute to hyperandrogenism progression and anovulation in PCOS patients." (PMID 32545404, 2020). "It has been reported that insulin resistance in lipoatrophic mice has been reversed by the combination of physiological doses of adiponectin and leptin, but only partially by either adiponectin or leptin alone." (PMID 33102570, 2020).
Insulin resistance (continued). "These may include low-grade systemic inflammation, HPA dysfunctions, leptin-resistance, insulin resistance, or ceramide-induced DNA methylation." (PMID 33173508, 2020). "Leptin may promote atherogenesis processes and insulin resistance and on the other hand, it may exert antiatherogenic effect and increase insulin sensitivity." (PMID 33198735, 2020). "Insulin resistance, systemic inflammation, oxidative stress, and higher leptin levels have been suggested as potential mechanisms that may explain the association between MetS and CRC." (PMID 33238496, 2020). "Taking into account the close connection between insulin resistance, leptin resistance and dysmetabolism with chronic low-grade inflammation it becomes imperative to understand the mechanisms under the basis of this connection and the role of peripheral nervous system in this scenario." (PMID 33353562, 2020). "Beyond fertility, follicle-stimulating hormone (FSH) may exert action on adipocytes, which are the major source of adiponectin and leptin, linking to insulin resistance." (PMID 33086618, 2020). "Finally, our study illustrates higher leptin levels along with greater insulin resistance in the female gender." (PMID 33680012, 2020). "In this study, we showed, for the first time, that alterations in serum adiponectin and leptin as well as insulin resistance were correlated with hepatic steatosis and hepatic fat contents in liver transplant recipients independent of traditional risk factors of hepatic steatosis." (PMID 32728230, 2020). "Furthermore, as the ratio of HMW adiponectin to total adiponectin and to leptin reveal propensities to insulin resistance and inflammation, we also examined them." (PMID 33042112, 2020). "In contrast, the sensitivity of tissues to leptin was diminished, leading to insulin resistance." (PMID 32937828, 2020). "Finally, leptin can reduce the antioxidative and lipogenic effects of insulin, promoting insulin resistance." (PMID 32403968, 2020). "The present findings provide a new insight into evidence that small-molecule Ca acts as a selective leptin-sensitizer in the liver through upregulation of endogenous Leprb expression, which attenuated hepatosteatosis, leading to improvement of insulin resistance and hyperglycemia in obese mice." (PMID 32792584, 2020). "Analysis of the interactions of differentially expressed microRNAs with gene expression pathways suggests the potential contribution of selected miRNAs in the regulation of the activity of genes associated with insulin resistance, fatty acids metabolism, and adipocytokine (TNF-α, leptin) signaling." (PMID 32069846, 2020). "Insulin resistance and T2D represent perturbed metabolic states in which intestinal sensitivity to key regulatory hormones such as insulin, leptin and glucagon-like peptide-1 (GLP-1) may be altered, contributing to increased CM secretion." (PMID 32231641, 2020). "Moreover, we found weak to moderate negative correlations between OB volume and BMI and related measures of metabolic health, especially leptin, body fat percentage, waist-height ratio and insulin resistance." (PMID 33328935, 2020). "However, the possible role of leptin concerning metabolic disarrangements, including insulin resistance in liver cirrhosis, is less known." (PMID 32092909, 2020). "While visceral or intra-abdominal fat has been found to contribute to leptin concentrations, insulin resistance and obesity-related diseases, there are only a few imaging studies documenting the preferential distribution of body fat to either the intra-abdominal or subcutaneous compartments in dogs." (PMID 32228685, 2020). "A high-fat diet may induce hyperleptinemia and hyperinsulinemia accompanied by leptin and insulin resistance and lower suppression of ghrelin secretion." (PMID 33114561, 2020). "The non-significant association between leptin and type 2 diabetes in women was entirely mediated by insulin resistance." (PMID 32131811, 2020).
Insulin resistance (continued). "We speculate that relative insulin resistance and changes in the leptin system might be the first evidence of processes promoting deleterious metabolic programming for post-natal life." (PMID 32778645, 2020). "Thus, insulin resistance, measured by HOMA-IR, mediated the association between leptin levels and incident type 2 diabetes." (PMID 32131811, 2020). "Therefore, in the current study we sought to assess the combined effect of central leptin and galanin on insulin resistance in the adipose tissues of type 2 diabetic rats." (PMID 32395890, 2020). "This study allowed one to conclude that the inactive and sedentary lifestyle of female adolescents, along with excess body fat, insulin resistance, and higher concentrations of high-sensitivity C-reactive protein are associated to the higher concentration of TNF-α, IL-6, and leptin." (PMID 32694929, 2020). "Furthermore, treatment with MK‐2206, an Akt inhibitor, blocked the combined effects of galanin + leptin on alleviation of insulin resistance." (PMID 32395890, 2020). "To date, it is unknown whether galanin can potentiate the effect of leptin on alleviation of insulin resistance." (PMID 32395890, 2020). "Moreover, the adiponectin/leptin ratio has been suggested as a maker of adipose tissue dysfunction and correlates with insulin resistance more closely than adiponectin or leptin alone or even the HOMA index, which is a surrogate of insulin resistance." (PMID 31694146, 2019). "The correlation between the leptin-to-adiponectin ratio and the anthropometric measurements, atherogenic index of plasma, lipid accumulation product, homeostatic model assessment of insulin resistance, interleukin 6, and high-sensitivity C-reactive protein was determined." (PMID 30457109, 2019). "Adiponectin levels in obese individuals significantly decrease, which, in combination with the observed increase in leptin level and activation of proinflammatory pathways, contributes to the development of insulin resistance and consequently also to type 2 diabetes." (PMID 31438646, 2019). "PTP1B has been the subject of interest in recent years as many reports firmly favor it as a promising target for T2DM as its expression in muscle and adipose tissue correlate with the degree of insulin resistance and the attenuation of leptin signaling pathways." (PMID 31395821, 2019). "Plasma leptin may even be involved in the development of hot flashes experienced by menopausal women, with participation of insulin resistance in this mechanism." (PMID 31509577, 2019). "Secretion of adipokines, such as leptin, adiponectin, and interleukin 6 from these fat depots might result in metabolic dysfunction including insulin resistance." (PMID 31289463, 2019). "NF-κB also activates the expression of the suppressor of cytokine signaling 3 (SOCS3) which promotes negative feedback in the insulin and leptin intracellular signaling pathways, potentially linking hypothalamic inflammation with central leptin and insulin resistance." (PMID 31057350, 2019). "The ratio of leptin and adiponectin concentrations, which correlates positively with the homeostasis model assessment of insulin resistance (HOMA-IR), may be an indicator of the development of metabolic complications." (PMID 31510055, 2019). "Other factors, such as glucose, insulin, cytokines, ghrelin, leptin, and other indices of insulin resistance may also participate in the abnormal lipid metabolism in diabetic patients." (PMID 31010439, 2019). "As both leptin and adiponectin are known to influence insulin sensitivity of metabolic tissues, reduced levels of leptin and adiponectin might play a role in the development of insulin resistance in liver and skeletal muscle, as seen in p110αDEL mice." (PMID 30948720, 2019).
Insulin resistance (continued). "Obese rats showed increased levels of fasting plasma glucose, insulin, insulin resistance (homeostatic model assessment-insulin resistance), total cholesterol, low-density lipoprotein cholesterol, inflammatory markers, and leptin compared to those in the control group." (PMID 31284705, 2019). "Some studies suggest that a low sodium diet might decrease insulin resistance by reducing blood leptin levels, bradykinin concentration and angiotensin II levels." (PMID 31461862, 2019). "Others hypothesise that increased adipose tissue increases circulating levels of adiponectin and leptin, inflammatory proteins, oxidative stress, insulin and insulin resistance and abnormalities in lipid metabolism." (PMID 31266462, 2019). "Notably, the levels of these three major adipokines—leptin, resistin, and adiponectin—were shown to correlate with insulin resistance." (PMID 31540528, 2019). "Hyperglycaemia and insulin resistance combined with increased leptin levels may have resulted in some of the changes observed in the subchondral bone of the HFS animals." (PMID 30846801, 2019). "Moreover, the hyperactivated STAT3 induces the suppression of the 3-phosphoinositide pathway and, as a result, provokes the leptin and insulin resistance in the hypothalamus, as was shown in mice expressing a constitutively active STAT3 in the POMC-neurons." (PMID 30870482, 2019). "Additionally, the leptin:adiponectin ratio, which is used as an index of insulin resistance along with HOMA-IR, was reduced in the CLE group." (PMID 31208033, 2019). "Furthermore, the obtained data is consistent with the results of other studies that also showed that an elevated leptin level potentiated insulin resistance and hypertension while adiponectin, on the contrary, possessed cardio-protective effects." (PMID 31341853, 2019). "In previous observational studies, more sedentary time was associated with increased maternal leptin, lipid levels and C-reactive protein levels but not with insulin resistance or glucose." (PMID 30840112, 2019). "Adipose tissue does not only contribute to NAFLD as a source of FA; adipocytes secrete adipokines that have protective effects against NAFLD, such as adiponectin and visfatin, as well as resistin and leptin, which contribute to hepatic steatosis and insulin resistance." (PMID 31771244, 2019). "HDL levels were previously found to negatively correlate with leptin and positively correlate with adiponectin in a healthy cohort, suggesting a link between leptin, insulin resistance, and the metabolic syndrome, as well as a cardioprotective role for adiponectin." (PMID 31540528, 2019). "Furthermore, overexpression of GRP78 in the hypothalamus of obese Zucker rats resulted in reduced body weight by increasing BAT thermogenesis, decreasing leptin and insulin resistance, and reducing hepatic steatosis." (PMID 30209265, 2018). "Leptin and resistin are also related to obesity, insulin resistance, and inflammation." (PMID 30400222, 2018). "Localized increases of suppressor of cytokine signaling 3 (SOCS3), known as an inhibitor of leptin and insulin signaling specifically in the hypothalamus, may lead to leptin and insulin resistance." (PMID 29498693, 2018). "Leptin is known to be secreted in proportion to adipose tissue size and may induce insulin resistance." (PMID 29562620, 2018). "The changes described in the preliminary results confirm prior studies, including the higher levels of leptin and ghrelin, the increase in the inflammatory/cardiovascular risk marker, CRP, and the presence of insulin resistance in the subjects with higher BMI levels." (PMID 30400254, 2018). "To examine the role of adipocyte hormones and LPS in reduced insulin sensitivity in HIV patients, in the present study, we investigated the role of adiponectin, leptin, visfatin and LPS plasma levels in the insulin resistance of HIV-infected patients treated with HAART." (PMID 29434676, 2018).
Insulin resistance (continued). "Here, we also found that s-resistin expression is increased in 24-month-old Wistar rats, which have been considered as a pre-diabetic model with central leptin and insulin resistance accompanied by peripheral insulin resistance, hyperlipidemia and increased adiposity." (PMID 29500410, 2018). "However, it appeared that changes of adiponectin in postmenopausal women were independently related to leptin and insulin resistance values." (PMID 29772836, 2018). "The development of this insulin resistance in the liver may result from the lower control of fructose metabolism by insulin or the adipokine leptin." (PMID 29323186, 2018). "Furthermore, ROC curve analyses demonstrate the diagnostic potential of resistin/RBP4 and MCP-1/RBP4 indexes for T2DM and β-cell function while leptin/MCP-1 index is an additional indicator for insulin resistance/sensitivity." (PMID 29785210, 2018). "However, the increased levels of SOCS proteins can induce insulin resistance in peripheral organs and leptin resistance in the central nervous system." (PMID 29312471, 2018). "Authors have reported a relationship between Vitamin D, insulin resistance and leptin level." (PMID 29885650, 2018). "Additionally, other pathways such as ‘reversal of insulin resistance by leptin’ were also enriched for the overlap network, indicating that certain beneficial pathways are triggered irrespective of the level and duration of caloric restriction." (PMID 30380678, 2018). "A possible explanation for reduced leptin levels in persons with type 2 diabetes may be due to insulin resistance, a modulator of leptin production." (PMID 29422086, 2018). "Increased release from metabolically active abdominal fat of substantial adipokines, such as tumor-necrosis factor-α, free fatty acids, leptin and inflammatory markers, and reduced release of adiponectin, contribute to development of insulin resistance, compensatory and chronic hyperinsulinaemia." (PMID 30631750, 2018). "In experiments performed with mice of 6 weeks feeding with fructose plus melatonin, melatonin reverted the effects of visceral fat accumulation, the increase in leptin and uric acid and insulin resistance, and the increase in blood pressure by fructose treatment with melatonin." (PMID 30154843, 2018). "Therefore, in the presence of increased adiposity and insulin resistance, certain adipokines are affected, including adiponectin, leptin, and resistin." (PMID 29601521, 2018). "Stimulated leptin levels also had significant interactions with insulin sensitivity (homeostasis model of insulin resistance, P = 0.01), triglycerides (P = 0.0078), fasting glucose (P = 0.027), systolic blood pressure (P = 0.037), and high-sensitivity C-reactive protein (P = 0.027)." (PMID 29434574, 2018). "However, insulin resistance, reactive oxygen species and oxidative stress, hormones (e.g., leptin), cytokines, growth factors, and other metabolic reactions have also been linked to CAD and cancer." (PMID 30486335, 2018). "However, as pregnancy progresses, a surge of local and placental hormones, including estrogen, progesterone, leptin, cortisol, placental lactogen, and placental growth hormone together promote a state of insulin resistance." (PMID 30373146, 2018). "The glucose-lowering effect of foxtail millet might be a result of the interaction of increased leptin concentrations, decreased insulin resistance and reduced inflammation." (PMID 30326632, 2018). "For example, the present findings in lipodystrophic mice suggest the feasibility of an alternative FATS-controlled cell-based therapy for lipoatrophic diabetes via combined expression of leptin and adiponectin, which has been shown to completely reverse insulin resistance in lipoatrophic mice." (PMID 30219861, 2018). "In our correlation model, leptin demonstrated a negative correlation with insulin, which has been shown to play a role in the modulation of insulin resistance in subjects undergoing a weight loss program." (PMID 30405010, 2018).